CD4 (CD4 molecule)
Diseases named in the same sentence as CD4 in open-access papers (continued):
Sharing a sentence is not in itself a finding about the gene and the disease.
spondyloarthritis (14 papers, 2006 to 2026). "Murine models of inflammation suggest that co-expression of GM-CSF and IL-17A by CD4 T cells marks out a pathogenic subset of Th17 cells, and neutralisation of GM-CSF in the Sagakuchi model of spondyloarthritis causes improvement in joint inflammation." (PMID 29142230, 2017). "Consistent with our imputed findings, IL-27 treatment prior to disease onset in the HLA-B27-transgenic rat spondyloarthritis model inhibited spondyloarthritis development through suppression of IL-17/TNF production by CD4 + T-cells." (PMID 40709250, 2025). "It should be noted that doses of 2 × 103 IU/rat in HLA-B27 with spondyloarthropathy had a weak effect on CD4+ Treg induction." (PMID 36635667, 2023). "We observed CD4 cells to be the largest population of GM-CSF-producing cell in both spondyloarthritis peripheral blood and synovial fluid, with significant contributions from CD8 and CD56 cells." (PMID 29142230, 2017). "We did however note increased GM-CSF+ CD4 T cells in patients on anti-TNF therapy, but even with the exclusion of these patients from the analysis, GM-CSF+ CD4 cells were still elevated in spondyloarthritis compared to controls." (PMID 29142230, 2017). "We here show that human spondyloarthritis is characterised by a program of lymphoid GM-CSF production in multiple compartments, including CD4 and CD8 T cells, γδ and innate lymphoid cells (ILC)." (PMID 29142230, 2017). "We used Boolean gating to delineate the functional overlap of IL-17A, IFN-γ and GM-CSF production by CD4 T cells in healthy controls, spondyloarthritis and RA." (PMID 29142230, 2017). "We purified ex vivo CD4 IL-17A+ cells by single cytokine capture from 4 spondyloarthritis, 4 RA and 3 healthy controls." (PMID 29142230, 2017). "Here we show increased numbers of GM-CSF-producing CD4 and CD8 lymphocytes in the blood and joints of patients with spondyloarthritis, and increased numbers of IL-17A+GM-CSF+ double-producing CD4, CD8, γδ and NK cells." (PMID 29142230, 2017). "Taken together, our data suggest an important function in human spondyloarthritis for GM-CSF production by multiple lymphocyte populations, including CD4, CD8 and γδ T cells and ILCs, within the context of globally enhanced type 17 immunity." (PMID 29142230, 2017). "Both GM-CSF+ and IL-17A+GM-CSF+ double-producing CD4 T cells express increased levels of GPR65, a proton-sensing receptor associated with spondyloarthritis in genome-wide association studies and pathogenicity in murine inflammatory disease models." (PMID 29142230, 2017). "IL-17A+ CD4 cells (Th17 cells) were increased in spondyloarthritis compared to both control groups." (PMID 29142230, 2017). "Additionally, synovial tissue cultures of CD4 T cells from 4 spondyloarthritis patients showed comparable high levels (>30%) of GM-CSF production." (PMID 29142230, 2017). "Moreover, similar, but not significant results (p = 0.0919) could be observed in an autologous setting using mDCs and CD4+ T cells from patients with spondyloarthritis." (PMID 30555457, 2018). "The levels of GM-CSF-producing CD4 and CD8 lymphocytes were shown to be increased in the blood and joints of patients with spondyloarthritis, and G protein-coupled receptor 65 was found to mediate GM-CSF production." (PMID 35835809, 2022). "However, both IL-17A−GM-CSF+ CD4 cells and double-positive IL-17A+GM-CSF+ CD4 and CD8 cells were markedly increased in spondyloarthritis synovial fluid relative to blood." (PMID 29142230, 2017). "In addition, we found these cells did not express CD4, CD8, nor γδ T cell receptors, thus resembling RORγt+ CD3+ CD4−CD8− entheseal resident T cells, reported to be induced by IL-23 in a mouse spondyloarthropathy model." (PMID 27905482, 2016).
squamous intraepithelial lesions (14 papers, 2007 to 2025). "Low-grade squamous intraepithelial lesion (LSIL) and high-grade squamous intraepithelial lesion (HSIL) were associated with CD4 cell count<200Í106/L, P=0.021 and P<0.001, respectively." (PMID 26005687, 2015). "Evidence showed that immune-suppression and low CD4 counts caused by HIV infection predisposes women living with HIV infection at an increased risk for CC and the development of squamous intraepithelial lesions." (PMID 31744548, 2019). "High rates of anal high-grade squamous intraepithelial lesions among HIV-positive men, at all CD4 levels but with lower CD4 counts, have been associated with earlier development of high-grade squamous intraepithelial lesions (p = 0.007)." (PMID 18094898, 2007). "In severe or high-grade squamous intraepithelial lesions (SIL) of patients with CC, the increased CEACAM-1 and TIM-3 interaction further suppresses the antitumor activity of CD4+ and CD8+ T cells." (PMID 37508372, 2023). "The association between abnormal cervical cytology and HIV infection status in women was evaluated to correlate with CD4 cell count and viral load in HIV-positive patients with the presence of low-grade (LSIL) and high-grade squamous intraepithelial lesion (HSIL)." (PMID 22888358, 2012).
synovitis (14 papers, 2010 to 2025). Inflammation of a synovial membrane. "Our demonstration that the local presence of IL-17 producing CD4+ T cells (either Th17 or IL-17+IFNγ+ T cells) in the RA joint is associated with active synovitis measured by PDUS, provides novel mechanistic insight into PDUS-related immunopathology." (PMID 20824142, 2010). "Together, these data indicate that PDUS-defined active synovitis is associated with the presence of local IL-17-producing CD4+ T cells." (PMID 20824142, 2010). "Equipped with tissue-invasive features, RA CD4+ T cells rapidly induce synovitis in a human synovium mouse chimera model." (PMID 36861127, 2023). "The data suggest a role for CD4+CD161+ T-cells in the early immune events leading to clinical synovitis." (PMID 24223933, 2013). "In the present study, we found that CX3CR1+CD4+ T cells contribute to synovitis in LORA." (PMID 39910629, 2025). "Furthermore, when equine sdMSCs were administered in lipopolysaccharide induced synovitis in vivo, CD4+ and CD8+ lymphocytes increased and CD4+/CD8+ double-positive lymphocytes decreased." (PMID 34779250, 2022). "CD4+T cells, mast cells, and macrophages play an essential role in synovitis." (PMID 35902862, 2022). "The presence of this cytokine initiates the differentiation of Naïve CD4+ T cells towards a Th1 response, so according to the observed increase of IL-12p40, here we hypothesize that this antigen-induced synovitis model is dominated by a local Th1 response." (PMID 28388908, 2017). "We hypothesized that CD4+CD161+ cells representing Th17 lineage cells may be modulated prior to or after development of clinical synovitis." (PMID 24223933, 2013). "The small number of synovial CD4-positive lymphocytes found in the samples of both study groups, consisting of HHV-7 PCR+ and HHV-7 PCR−, was in line with low-grade synovitis." (PMID 32825448, 2020). "Based on that, and taking into account that the presence of large numbers of activated CD4+ T cells in synovial tissue is important in the pathogenesis of chronic synovitis, here we suggest that synovial T cell distribution could be suitable biomarker in the evolution of synovitis." (PMID 28388908, 2017).
tuberculous pleurisy (14 papers, 2008 to 2025). "This study analyzed DNA methylation and transcriptome data from macrophages and CD4+ T cells from pleural lavage fluid of BCG‐induced tuberculous pleurisy mouse models at specific time points (Days 0, 1, 7, and 14)." (PMID 40170749, 2025). "There were increases in the percentage of the CD3 and CD4 T cells in the pleural fluid compared with values in the blood with statistical significance in tuberculous pleurisy." (PMID 27275329, 2016). "In this study, we amplified TCR α and β chains from expanded peptide-responsive CD4+ T cells that were separated from ELISPOT-positive PLF mononuclear cells that were obtained from patients with active tuberculous pleuritis." (PMID 23209409, 2012). "ADA analysis is a sensitive marker of tuberculous pleuritis even in HIV patients with very low CD4 counts in a high TB endemic region." (PMID 18665218, 2008). "We have shown that ADA offers a high sensitivity and is rapid for the diagnosis of tuberculous pleuritis in HIV patients with low CD4 counts in a high TB endemic region." (PMID 18665218, 2008). "Previous studies evaluating the usefulness of ADA for the diagnosis of tuberculous pleuritis have either a very small number of HIV positive cases or patients with higher mean CD4 counts." (PMID 18665218, 2008). "However, following stimulation with MTB-specific peptides of ESAT-6/CFP-10, CD4+CD69+ T cells from the same patients with tuberculous pleurisy expressed high levels of IFN-γ, IL-2 and TNF-α, indicating that the response was MTB-specific." (PMID 21887301, 2011). "The aim of this study was to evaluate the sensitivity of ADA in tuberculous pleuritis patients with low CD4 counts and to determine whether there was any correlation between CD4 cell counts and ADA values." (PMID 18665218, 2008). "During the continuous infection of BCG‐induced tuberculous pleurisy mouse models, the difference in DNA methylation profile between macrophages and uninfected tissues was most pronounced on Day 1, while the difference between CD4+ T cells and uninfected tissues became increasingly evident over time." (PMID 40170749, 2025). "In our previous study, we have demonstrated that both CFP10-specific CD4+ and CD8+ T cells were present in patients with tuberculous pleurisy (TBP)." (PMID 24349220, 2013). "Our data suggest that compared to patients without TPE, patients with tuberculous pleurisy have a two-fold higher chance of being CD4+IL-9+ T cell positive." (PMID 34925358, 2021). "Recent findings suggest that the immunogenic reaction in tuberculous pleurisy involves lymphocytes (including CD3, CD4, CCR4, and Th17 cells), neutrophils, mesothelial cells, and various cytokines such as interferon-γ, interleukin (IL)-8, IL-12, and monocyte chemoattractant protein-1." (PMID 23317113, 2013). "In addition, CD4+ T cells expressing different combinations of IFN-γ, IL-2, TNF-α, IL-17A, and IL-22 have been described in tuberculous pleurisy." (PMID 23451159, 2013). "One of the major concerns regarding the sensitivity of ADA was its reliability in immunocompromised patients; however, more recent studies have demonstrated that ADA is a reliable marker of tuberculous pleurisy in HIV-positive patients, even in those with a low CD4 T-cell count." (PMID 22723878, 2012). "In this study, we found that MTB-specific peptides of ESAT-6/CFP-10 can stimulate the expression of CD40L specifically in CD4+ T cells but not other cells from pleural fluid cells (PFCs) in patients with tuberculous pleurisy (TBP)." (PMID 21625607, 2011). "Similarly, if a patient has a negative result of CD4+IL-9+ T cells, he would have a 0.18% chance of being a tuberculous pleurisy patient." (PMID 34925358, 2021). "Elevated CD3, CD4, CCR4 and Th17 cells and decreased mast cells and GATA-3+ cells in the parietal pleura distinguish patients with untreated tuberculous pleurisy from those with nonspecific pleuritis." (PMID 21829471, 2011).
tuberculous pleurisy (continued). "The number of CD3+, CD4+ and CCR4+ cells and the expression of RORC2 mRNA were significantly increased in the tuberculous pleurisy patients compared with the nonspecific pleuritis subjects." (PMID 21829471, 2011).
vaginal infection (14 papers, 2010 to 2024). "Our investigation was correlated to the previous study that PmpG-combined DDA/TDB adjuvant significantly enhanced IFN-γ expression in CD4+ T cells and reduced Chlamydial shedding against vaginal infection by C. muridarum." (PMID 35529835, 2022). "Here we demonstrate that the course and resolution of vaginal infection is strictly correlated to the presence of IL-17 secreted locally by CD4 vaginal T cells." (PMID 21818387, 2011). "CD4 T cells recovered from the FRT at day 14 post vaginal infection were assessed by flow cytometry following brief PMA/ionomycin stimulation in the presence of Brefeldin A. As expected, CD4 T cells in the FRT of Chlamydia-infected mice produced significant amounts of IFN-γ, but negligible IL-4." (PMID 35196366, 2022). "An effective microbicide must prevent HIV infection in several target cells (CD4-expressing, CD4-non-expressing), as well as in the presence of concurrent vaginal infections due to other viral, bacterial, parasitic, or fungal microorganisms." (PMID 33321835, 2020). "HIV status and CD4 category did not significantly modify the hazard ratios for vaginal infections with HPV clearance." (PMID 21869857, 2011). "However, analysis was limited to the secondary lymphoid tissue in mice that were not given a vaginal infection since undetectable numbers of PmpG-Tet+ CD4+ T cells were found in the GT of these mice." (PMID 28106821, 2017). "Virus is able to reach the central nervous system more quickly after vaginal infection in mice deficient in CXCL10, and trafficking of NK cells and HSV-specific CD8+ T-cells (but not CD4+ T-cells) to infected tissue is impaired in both CXCL9 and CXCL10-deficient mice." (PMID 21283640, 2011).
Airway obstruction (13 papers, 2009 to 2026). Obstruction of conducting airways of the lung. "Our results show that CD4 T cells are necessary to mediate all disease parameters associated with FI-RSV VED including airway obstruction, weight loss, and AHR." (PMID 25769044, 2015). "We next investigated other immunological factors related to the CD4 T cell response that could mediate either the severe weight loss or airway obstruction associated with FI-RSV VED." (PMID 25769044, 2015). "This is in line with other studies having shown that vaccine-induced circulating TNFα-producing CD4+ and CD8+ T-cells mediate weight loss, pulmonary dysfunction and airway obstruction upon RSV infection." (PMID 39472590, 2024). "Allergen-activated CD4 T cells in the airways play a key role in eosinophil recruitment, inflammatory response, and mucus production, ultimately leading to airway obstruction in asthmatics." (PMID 36733482, 2023). "Depletion of CD4 T cells prior to RSV challenge, led to a significant (p<0.05) amelioration of both airway obstruction and weight loss in FI-RSV-immunized mice." (PMID 25769044, 2015). "Similar results were also reported by Gupte and colleagues who found that prior TB infection associated with an excess loss of FEV1, and that although older age, smoking and higher CRP associated with obstructive lung disease, CD4 count and ART did not." (PMID 31830103, 2019). "We were unable to assess effects of HAART on progression of airway obstruction or to determine effects of length of HAART use, HAART compliance, or nadir CD4 cell count, as this information was not reliably available." (PMID 19621086, 2009).
amyloid (13 papers, 2010 to 2025). "AD-associated risk genes, including APP, PICALM, and RBFOX1, were positively correlated with plasma cells, activated CD4+ T cells, and Tregs, linking amyloid-related pathways to adaptive immune activation." (PMID 41567547, 2025). "By using a GLM with sex and age as covariates on T cell subsets, we found that CD8+ effector T cells and CD57+ KLRG1+ CD4+ terminally differentiated effector memory T cells were higher in MCI patients with amyloid pathology." (PMID 38658964, 2024). "When naïve and effector-like CD38variable CD4+ T cells were measured both cognitively normal and cognitively impaired amyloid positive participants had increased numbers." (PMID 37737298, 2023). "IL-1β increases IL-4 production, a potent modulator of CD4 T cell responses, and administration of IL-4 in AD mice induces amyloid plaque clearance." (PMID 31822279, 2019). "Indeed, administration of Aβ-specific type 1 (TH1) and type 17 (TH17) CD4+ T cells (two specialized populations of CD4+ T cells characterized by specific secretory profiles) reportedly exacerbates memory impairment and amyloid deposition in APP-PS1 mice." (PMID 38594240, 2024). "It is possible that CD4 + T cells play a role in the pathogenesis of AD through their interaction with microglia, their involvement in immune mechanisms, and their role in facilitating amyloid clearance." (PMID 38478169, 2024). "In line with effector CD4+ T cells being reported as beneficial against AD, other studies have shown a negative effect of CD4+regulatory T cells (Tregs) in AD, with their depletion in mice resulting in reduced amyloid load as well as improved learning and memory." (PMID 38600001, 2024). "In other animal studies, however, IFN-γ-dependent targeting of Aβ-specific Th1-polarized CD4+ cells to amyloid plaques was shown to reduce amyloid pathology without promoting toxic neuroinflammation." (PMID 26558367, 2015). "In addition, co-staining of Aβ (blue), CD4 (red), and CD8 (green) T cells revealed the occurrence of both of these lymphocyte subpopulations in the perivascular space and at amyloid plaques." (PMID 20520819, 2010).
aplastic anemia (13 papers, 2008 to 2024). Anemia resulting from bone marrow failure (aplastic or hypoplastic bone marrow). "Indeed, MEG3, a long non-coding RNA can modulate TIGIT expression on CD4+ T cells from aplastic anaemia patients." (PMID 38077329, 2023). "Alloantigen-specific CD4+ T cells can contribute to GvH-driven aplastic anemia either directly, by recognition of major histocompatibility alloantigens on bone marrow precursors, or indirectly, by provision of help to minor histocompatibility alloantigen-specific CD8+ T cells." (PMID 19006695, 2008). "The finding of low CD4/CD8 was also found in HAAA compared to non-hepatitis-associated aplastic anemia, which could help predict the development of HAAA." (PMID 38675959, 2024). "The 3 young children in our study all had similar flow cytometry profiles with high percentages of CD8+ CD103+ TEM cells that were HLA-DR+, had low CD4:CD8 T-cell ratios, and 2 of them developed aplastic anemia." (PMID 37267251, 2023). "In aplastic anemia, γ-secretase inhibitor reduced T-bet expression and IFN-γ production, thus inhibiting the differentiation of Th1 cells from CD4+ T cells in vitro and in vivo." (PMID 33224898, 2020). "Previously, we demonstrated the overexpression of PD-1 on CD4+ and CD8+ T cells and elevated serum levels of sPD-1 in patients with aplastic anemia." (PMID 26608464, 2015). "Using experimental models for aplastic anemia, T cells were proposed as key mediators of hematopoietic dysfunction and ultimately BM failure, and in experimental ehrlichiosis, infection-induced expansion of LSK cells was shown to be dependent upon IFNγ production by CD4+ T cells." (PMID 28671989, 2017).